ELF3 (E74 like ETS transcription factor 3)
Diseases named in the same sentence as ELF3 in open-access papers (continued):
Sharing a sentence is not in itself a finding about the gene and the disease.
tumor (continued). "We identify crucial genes including ELF3 in mediating the interactions among tumor cells and their TME components, suggesting that ELF3 could be a therapeutic target in LUAD for future drug discovery." (PMID 33144684, 2021). "There has been significant recent interest in the role and function of ELF3 and other members of the ETS-related transcription family in part because of multiple observations of differential gene-expression profiles across cancer tumour datasets." (PMID 30148686, 2019). "Although ELF3 overexpression in A549 control cells did not significantly increase xenograft tumor growth, the modest ELF3 rescue in clonal A549 shELF3 cells restored the ability to establish tumors in vivo." (PMID 31780666, 2019). "Conversely, ELF3 may have a pro-tumorigenic role in HER2+ tumours, where ELF3 is upregulated due to HER2-signaling driven activation of the ELF3 promoter." (PMID 30200227, 2018). "The average durations of DFS and OS in patients with high level circulating CK7, ELF3, EGFR, and EphB4 mRNAs (tumor PBMCs vs. positive control: >2-fold) were significantly shorter than those of patients with normal or downregulation of the four mRNAs in the PBMCs." (PMID 27827952, 2016). "Like Spink1, the preferential overexpression of Elf3 in the CD133+ cells and also in the HCC tumor bulk in both proto-oncogene driven and inflammation-associated HCC tumor models was also apparent, while Elf3 expression was not altered or at a much lesser extent in the regenerating liver." (PMID 38030644, 2023). "One explanation for the results showing ELF3 as a repressor is that the experiments were carried out in AR‐responsive LNCaP cells and it is very likely that the advanced cancers where there is amplification of ELF3 would be castration‐resistant tumours where androgen is no longer the driver." (PMID 35472129, 2022). "This could also explain the variation in tumour immunostaining where some tumours are ELF3 negative and some are positive; there could be a correlation with the presence or the absence of AR, as ELF3 is known to act as a repressor of AR." (PMID 35472129, 2022). "Similarly, in triple negative breast cancer (TNBC), ELF3 mRNA expression is lower in primary tumours compared to normal breast epithelium, and further reduced in distant metastases." (PMID 30200227, 2018). "However, we did not observe such tumor nodule formation in animals injected with ELF3-overexpressing cells." (PMID 28199976, 2017). "All of the four circulating mRNAs, including CK7, ELF3, EGFR, and EphB4 mRNA, were strongly associated with NSCLC patients’ prognosis; however, the association of the cell-free RNA content with patient survival was independent of the tumor stage." (PMID 27827952, 2016). "By contrast, the over-expressed genes in the networks may trigger tumorigenesis of HNSCC by altering gene expression associated with inflammatory, proliferation, apoptosis and other processes, such as IL6, IGFBP3, ELF3, and PTGES in the both subgroups of tumor cells." (PMID 24069219, 2013). "Here, we find that ELF3 is overexpressed in LUAD compared with non-malignant lung and LUSC, and promotes oncogenic phenotypes including the requirement for tumor growth in vivo." (PMID 31780666, 2019).
cancer (80 papers, 2010 to 2026). A tumor composed of atypical neoplastic, often pleomorphic cells that invade other tissues. "As a member of the ETS family, ELF3 shares fundamental functions with other members, such as DNA binding and gene regulation, but differs in tissue specificity, cancer association, and the regulation of inflammation and immunity." (PMID 40162781, 2025). "Mutations in ELF3 have been identified in various types of cancers, including bladder, cervical, ovarian and gastrointestinal cancers." (PMID 38520216, 2024). "They observed a cluster with high expression of MUC1 and ELF3, estrogen-associated genes that influence cancer cell proliferation, migration, and invasion." (PMID 39229264, 2024). "For example, a multi‐omics analysis of GBC samples revealed frame‐shift mutations in ELF3 that generated cancer‐specific neoantigens activating T cells, which are promising candidates for cancer vaccine." (PMID 39428382, 2024). "We first investigated the association between ELF3 expression levels and both epithelial and mesenchymal programs across cancer cell lines." (PMID 36864480, 2023). "In contrast, in oral and ovarian tissue, the development of cancer is associated with a loss of ELF3 expression." (PMID 35472129, 2022). "Results from other tissues vary; in the colon, liver and lung, ELF3 expression appears to be associated with cancer progression and metastases." (PMID 35472129, 2022). "In particular, frame shift mutations in ELF3 led to the identification of several immunogenic cancer neoantigens." (PMID 33212880, 2020). "As molecular cancer subtype information is valuable in guiding clinical management, we examined the effect of driver mutation status on ELF3 expression and searched for patterns of co-occurrence or mutual exclusivity at the DNA-level." (PMID 31780666, 2019). "Loss of ELF3 in epithelial cells results in epithelial cell differentiation and cancer, as well as many other diseases." (PMID 29523781, 2018). "Mutations in ELF3, particularly inactivating mutations, occur in bladder, cervical, ovarian and a number of gastrointestinal cancers, including cancers of the biliary tract, stomach and colon." (PMID 30200227, 2018). "Notably, ELF3 loss in bile ducts, commonly observed in cancers, leads to ZEB2 and EMT-related protein upregulation, reducing cell-cell junction proteins and increasing cell motility." (PMID 40204777, 2025). "Moreover, a majority of ELF3 alterations are frame-shift mutations that contribute to cancer-specific neoantigens that activate T-cells, which indicates that they are cancer vaccine candidates." (PMID 39219440, 2024). "The role of ELF3 as a regulator of epithelial plasticity led us to query whether ELF3 is associated with clinical outcomes in cancer." (PMID 36864480, 2023). "Finally, ELF3 levels are associated with cancer patient survival in a lineage- and cancer-specific manner, highlighting the clinical relevance of ELF3 in specific cancer types." (PMID 36864480, 2023). "Likewise, mutations in ELF3 in many cancer tissues have also been deposited in the TCGA dataset, whereas those in EHF have not." (PMID 33712555, 2021). "However, in LP cells, which naturally experience higher replicative stress, this ELF3-related mechanism may make them more susceptible to transformation into cancer cells." (PMID 41498327, 2026). "Thus, ELF3 appears to associate with patient survival in a cancer-specific manner." (PMID 36864480, 2023). "ELF3, an ETS transcription factor, has been linked to cancer progression; however, the mechanisms regulating its activity remain incompletely understood." (PMID 42198413, 2026).
cancer (continued). "Another cyclin gene, CCNE1 also showed a trend for higher amplification frequency in ELF3/HNF4A up-regulated cancers (Student’s t-test p = 0.06)." (PMID 41425714, 2025). "ELF3, a transcription factor, is epithelial-specific and has been reported to be able to participate in cancer cell proliferation and migration, the EMT pathway, and epithelial tumor invasion." (PMID 38517922, 2024). "Aberrant expression of ELF3 has been found in various tumors and it acts as a promotor or suppressor for the malignant development of cancer cells." (PMID 39572025, 2024). "It has been found that ELF3 was one of the genes up-regulated in malignant tumor cells and was able to up-regulate the expression of tumor genes associated with proliferation and anti-apoptosis." (PMID 39572025, 2024). "CLDN4 and ELF3 expression was testified in all clusters and statistically significant increased expression of them were observed in cancer cell clusters C2, C5, and C7, indicating the similar expression status discovered in total cells." (PMID 38629624, 2024). "Together, these analyses suggest that ELF3 strongly correlates with an epithelial state across cancers." (PMID 36864480, 2023). "These trends were consistent in TCGA cancer types as well, further suggesting that ELF3 correlates with an epithelial phenotype." (PMID 36864480, 2023). "We next tabulated ELF3 expression levels with respect to the median epithelial ssGSEA scores in a given cancer type." (PMID 36864480, 2023). "This argument is further strengthened by tissue-specific survival trends seen for ELF3 expression levels across cancer types." (PMID 36864480, 2023). "Next, we examined the correlation of ELF3 with these scores in the CCLE cohort in a cancer type-specific manner." (PMID 36864480, 2023). "EHF and ELF3 play important roles as cancer‐promoting TFs in various cancers, their involvement in HRR has not been reported." (PMID 37702443, 2023). "TFs associated with PIK3CA mutations were involved in WNT signaling, epithelial–mesenchymal transition, and cancer stem cell transition, including ELF3, TFEC, STAT4, STAT5B, NFATC1, GLIS1, CDC5L and AR." (PMID 36243974, 2022). "For example, in metastatic lymph nodes in several cancer types, the increased expression of Esx/Elf3 correlated to an increased expression of EPCAM." (PMID 36230521, 2022). "A growing body of research shows that ELF3 can exhibit both tumor suppressor and oncogenic functions in cancers, a property seen in many transcription factors with dual biological function (both transcription activation and repression)." (PMID 36383615, 2022). "Some more advanced, less differentiated cancers of Gleason grade ≥ 7 were positive for ELF3 expression." (PMID 35472129, 2022). "ELF3 has been reported to play significant roles in the development and progression of human cancers." (PMID 36383615, 2022). "Previous studies have reported that ANF reduces cancer cell stemness via inhibition of the PKCί–ELF3–NOTCH3 axis and downregulates signaling pathways including the PI3K/Akt and ERK pathways." (PMID 34830169, 2021). "We were particularly interested in studying those genes that are associated with cancer progression, TME signals, and poor prognosis such as LY6E, NAPSA, MUC1, ELF3, and FOS." (PMID 33144684, 2021). "On the contrary, several studies claim that NEAT1 acts through direct interaction with specific mRNAs (e.g., ELF3) or via sponging certain miRNAs thereby promoting cancer cell growth, invasion, and migration." (PMID 32727085, 2020).
cancer (continued). "Our pan-cancer analyses from TCGA revealed that aberrant expressions of ELF3, EHF, and TGIF1 are prevalent in a wide spectrum of cancers and high levels of these master TFs are associated with poor patient outcomes." (PMID 33070167, 2020). "This included E74 like ETS transcription factor 3 (ELF3), spen family transcriptional repressor (SPEN) and notch receptor 3 (NOTCH3) that are known to be mutated in various cancers." (PMID 31438645, 2019). "It was previously reported that RII is transcriptionally regulated by Elf3 in some cancer cell lines." (PMID 31150422, 2019). "Mirroring these studies, we find that ELF3 cancer-specific networks include NXK2–1, a regulator of fetal lung development and oncogenic potential in LUAD38." (PMID 31780666, 2019). "Among Ets transcription factors, the epithelium-specific transcription factor Elf3 has been reported to modulate TGF-β signaling by regulating the transcription of RII in various cancer cells." (PMID 31150422, 2019). "Recent studies have shown that ELF3 is involved in cancer cell proliferation, differentiation, and migration in many human tumors." (PMID 29523781, 2018). "Conversely, gene amplification of ELF3 occurs in some of these same cancers (colorectal, gastric), as well as in breast and liver cancer." (PMID 30200227, 2018). "For TF AREB6, expression was found only in one malignant sample, while for PAX8 and ELF3 the expression pattern was present in normal and cancer samples." (PMID 20181230, 2010). "In addition, utilizing the CellMiner database, we found that among nearly sixty diverse human cancer cell lines, lower ELF3 expression is correlated with higher drug sensitivity to cisplatin and etoposide." (PMID 41498327, 2026). "In contrast, CDH1, encoding for E cadherin, showed a higher mutation rate in ELF3/HNF4A non-up-regulated cancers (16.7% vs. 6.1% in the up-regulated group), which was not however statistically significant (Student’s t-test p = 0.17)." (PMID 41425714, 2025). "Several neoantigens produced by ELF3 mutations are able to activate CD8 + T cells, suggesting that they may be potential cancer vaccine candidates." (PMID 39066855, 2024). "At present, the effect of ELF3 on the evolution of HPV16-positive cancers is rarely reported." (PMID 39572025, 2024). "Besides being a potential epithelial gatekeeper, ELF3 is also involved in maintaining cancer cell stemness." (PMID 36864480, 2023). "Elevated ELF3 activity induced by HPV16 may be reflective of possible links to cancer development or progression." (PMID 37031202, 2023). "Analysis of publicly- available in vitro transcriptomics data, including that from the Cancer Cell Line Encyclopedia (CCLE), and The Cancer Genome Atlas (TCGA) revealed that ELF3 is negatively correlated with mesenchymal factors and positively correlated with epithelial factors." (PMID 36864480, 2023). "When the number of genes whose expression was altered by ELF3, siRNA knockdowns was analysed, the cancer cells (PC3) possessed almost double the number of significantly altered genes (1848 upregulated, 931 downregulated) compared with BPH‐1 (776 upregulated, 664 downregulated)." (PMID 35472129, 2022). "Conversely, ELF3 overexpression was also reported in other cancers including lung adenocarcinoma." (PMID 36383615, 2022). "Such a compensation mechanism could render the efficacy of drug‐targeted ELF3 inhibition ineffective for longer‐term treatment of cancer cells." (PMID 35472129, 2022). "Given that NF-κB pathway plays essential roles in activating survival genes for cancer cells as well as inflammatory response in immune cells, we speculate that ELF3 may function as an important modulator of NF-κB pathway in LUAD." (PMID 33144684, 2021).
cancer (continued). "ELF3 is also reported to be associated with the TGF-β signaling pathway and EMT in some cancers." (PMID 33578820, 2021). "The ELF3 mutations are predominantly frame-shift alterations that result in several neoantigens that are able to activate CD8+ T-cells, confirming them as potential cancer vaccine candidates." (PMID 32839463, 2020). "Interestingly, 5 out of the top 10 hub genes in the network are cancer genes, including ELF3, SLC10A4, ANXA9, DEFB118, KRT8." (PMID 32064261, 2020). "Although ELF3 is currently poorly characterized in this regard, what is known ties ELF3 to both fetal lung development and airway tissue repair, functions that are often co-opted by cancer cells." (PMID 31780666, 2019). "An intriguing mechanism based on transcriptomic, proteomic, and metabolomic profiling of elF3 deletion mutants presented by Dieter A Wolf (USA, China), suggests a relationship between mRNA-specific translational control and altered energy metabolism in cancer." (PMID 28837155, 2017). "A comprehensive analysis of the human elF3 complex assembly in cells by Leos Valasek (Czech Republic) highlighted how imbalanced expression of elF3 subunits, frequently observed in cancer and developmental disorders, impacts on the overall functionality of elF3." (PMID 28837155, 2017). "The results demonstrated that patients with high ELF3 protein expression had significantly higher E-cadherin expression than did patients with low ELF3 protein expression (p = 0.002), suggesting that cancer cells of the former patient group had a more epithelial phenotype." (PMID 28199976, 2017). "In addition, there are other transcription factors related to cancer and cell movement that are significantly upregulated in this model, including ELF3 (8.7X higher in DU145-LN4) and ETV4 (7.5X fold higher level in DU145-LN4 compared to DU145 cells)." (PMID 24885350, 2014). "However, this cancer-associated role of ELF3 is distinct from our findings in normal mammary epithelia, where Claudin level remains unchanged." (PMID 40204777, 2025). "Notably, ELF3, which plays a critical role in epithelial cell differentiation and tumorigenesis, exhibits a mutation frequency of 12.65% in BLCA, significantly higher than in other cancers." (PMID 40867324, 2025). "As these mutations are associated with treatment resistance, their presence may counteract the lower risk clinicopathologic features associated with ELF3/HNF4A up-regulated cancers and could explain the lack of statistically significant differences in survival outcomes." (PMID 41425714, 2025). "Alterations in both ELF3 and IRF6 were significantly enriched in luminal A (typically ER-positive) cancers." (PMID 40790295, 2025). "Importantly, mutations within the conserved ETS domain in EHF and ELF3 abolish the ability of these proteins to inhibit EMT, and this subsequently promotes tumor growth and invasion in vivo, leading to a dominant negative fashion on EMT and cancer cell differentiation in vivo." (PMID 39362647, 2024). "These associations build on our findings in rafts and patient tissue, supporting the presence of an ELF3-driven differentiated squamous subpopulation in HPV+ disease processes, including cancer." (PMID 37031202, 2023). "In this Chinese PDAC cohort, KRAS mutations were mutually exclusive with P/LP alterations in BRAF, CTNNB1, ELF3, FGF19, and other cancer‐related genes." (PMID 36999792, 2023). "The human ELF3, a member of the ETS family of transcription factors, plays a role in the induction and progression of human cancers is well studied." (PMID 36383615, 2022).